PNPLA3 (patatin like domain 3, 1-acylglycerol-3-phosphate O-acyltransferase )
Diseases named in the same sentence as PNPLA3 in open-access papers (continued):
Sharing a sentence is not in itself a finding about the gene and the disease.
steatosis (continued). "The high-risk PNPLA3 GG variant LAMPS demonstrated increased steatosis, pro-inflammatory cytokine secretion, stellate cell activation, and secretion of the pro-fibrotic marker COL1A1, consistent with the clinical characterization of this polymorphism." (PMID 39324073, 2024). "The PNPLA3 mutation and initial steatosis grade were key predictors of MASLD improvement, while TM6SF2 (rs58542926) and MBOAT7 (rs641738) variants were not significant." (PMID 39125390, 2024). "This increase in lipid accumulation is consistent with findings reported by others and supports the view that loss of PNPLA3 function is associated with steatosis in patients." (PMID 39000384, 2024). "For predicting fibrosis, selected parameters in the univariate analysis included age, T2DM, HT, AST, platelet count, steatosis grade, and PNPLA3 and SIRT5 variants." (PMID 39596570, 2024). "The study identified the PNPLA3 G allele and pediatric age as independent factors associated with moderate/severe steatosis." (PMID 38397999, 2024). "Several studies have shown that the PNPLA3 I148M variant was also associated with an increased risk of steatosis and fibrosis in liver and kidney, and fat accumulation in this process is causally linked with liver fibrosis and kidney disease progression." (PMID 38825630, 2024). "The patatin-like phospholipase domain-containing 3 (PNPLA3) rs738409-G variant, also known as PNPLA3 I148M polymorphism, was the first and firmly recognized risk factor for steatosis." (PMID 38999436, 2024). "For example, a recent study in Japan demonstrated that the HSD17B13 rs6834314 AG/GG variants were associated with increased steatosis grading but exhibited an attenuated effect of PNPLA3 on advanced hepatic fibrosis." (PMID 39596570, 2024). "In the Discovery cohort, 114/172 patients (66.27%) had severe steatosis (grade 2-3) and 104/172 (60.46%) carried the PNPLA3 p.I148M variant." (PMID 36937355, 2023). "There was a multiplicative interaction between the p.I148M variant and female sex in determining steatosis in all groups, with a larger contribution of the PNPLA3 × sex interaction in women aged ≥55 years." (PMID 37749332, 2023). "A significant interaction between the PNPLA3 rs738409 variant and high-sweetened beverages consumption on steatosis severity was found, suggesting it increases its severity." (PMID 36830856, 2023). "Steatosis is caused by three main triggers: overload nutritional diet, high risky variant (PNPLA3 I148M) and predisposed monogenic lipid disorders (APOB or MTTP mutation)." (PMID 37009924, 2023). "With precise gene editing, we show that the effects of gene mutations or SNPs (as exemplified for PNPLA3 I148M) on steatosis risk can be addressed with high phenotypic resolution." (PMID 36823355, 2023). "We analyzed our sample cohort for the presence of PNPLA3 (I148M) variant carriers and identified a correlation between the variant carrier (CG/GG) with steatosis and steatohepatitis as well as with steatosis grade." (PMID 37686029, 2023). "In summary, hepatic IL-32 and CCL20 expression is increased in MASH samples with progressed activity (intense steatosis and moderate-to-severe fibrosis), and enhanced IL-32 expression was found to be related to the PNPLA3 I148M variant." (PMID 37686029, 2023). "One study found an association between the rs738409 PNPLA3 polymorphism and moderate/severe steatosis in WND." (PMID 37046505, 2023). "Compared with WT organoids, all of those variants resulted in steatosis: PNPLA3-KO yield highest steatosis score, followed by HO and HE." (PMID 37009924, 2023). "In this cohort, steatosis ≥ 2 was diagnosed in 232/358 patients (64.80%), whereas obesity (BMI ≥ 30 kg/m2) and the PNPLA3 I148M variant were identified in 194/358 (54.18%) and 255/358 (71.2%), respectively." (PMID 36937355, 2023). "PNPLA3 I148M polymorphism was more strongly associated with steatosis in people who consume sweet drinks." (PMID 37304843, 2023).
steatosis (continued). "The protective role of steatosis emerged from the evaluation of some genetic polymorphisms that are related to steatosis, such as single nucleotide polymorphisms (SNPs) in the PNPLA3 and TM6SF2 genes." (PMID 37632072, 2023). "While after 1 day of FFA exposure both PNPLA3 variant organoids presented with a similar steatosis degree, fat levels were consistently elevated in PNPLA3I148M/I148M organoids from day 2 onwards." (PMID 36823355, 2023). "A recent study has shown that the steatosis associated with the PNPLA3 variant is caused by the accumulation of PNPLA3 protein on lipid droplets." (PMID 36837886, 2023). "Our findings challenge this idea, because complete loss of PNPLA3 protein in human hepatocytes induces steatosis, highlighting important interspecies differences." (PMID 36823355, 2023). "The PNPLA3 gene mutation is associated with increased transaminase activity, which can promote the progression of liver fibrosis and steatosis." (PMID 35154322, 2022). "Patatin-like phospholipase domain-containing protein 3 (PNPLA3) is a genetic variant that has been found to be associated with steatosis, inflammation, cirrhosis, and HCC." (PMID 35165568, 2022). "In the multivariate models, the PNPLA3 represented a risk factor for steatosis grade ≥2 (OR = 2.27, 95% CI 1.24–4.15; p = 0.008) and grade 3 (OR = 3.69, 95% CI 1.56–8.70; p = 0.003)." (PMID 36555467, 2022). "The present study also underlined the influence of PNPLA3 rs738409 genotype independently associated with progressive steatosis after HCV clearance." (PMID 35696400, 2022). "PNPLA3 rs738409 C>G p.I148M is associated with steatosis and fibrosis and an increased risk of cirrhosis and hepatocellular cancer." (PMID 36454904, 2022). "To date, only few studies offer possible explanations for the underlying mechanism, suggesting that steatosis is triggered by the accumulation of PNPLA3(I148M) protein at LDs." (PMID 36611868, 2022). "In univariate and multivariate analyses, the presence of diabetes and PNPLA3 CG+GG genotypes and increased BMI at FUw72 were significantly associated with progressive steatosis after SVR." (PMID 35696400, 2022). "In multivariate analysis, the presence of diabetes, PNPLA3 CG+GG genotypes and increased BMI at FUw72 were significantly associated with progressive steatosis after SVR." (PMID 35696400, 2022). "In a meta-analysis, the pooled results have showed that PNPLA3 rs738409 is associated with an increased risk of advanced fibrosis and steatosis in chronic HCV infection." (PMID 35696400, 2022). "The findings reported in animal models were also supported by human genetic studies which showed that PNPLA3 rs2294918 E434K variant decreased PNPLA3 expression, reducing the effect of the I148M variant on the predisposition to steatosis and liver damage." (PMID 34040583, 2021). "The donor TM6SF2 (transmembrane 6 superfamily member 2) c.499A allele is an independent risk factor of liver graft steatosis following LT in addition to the effects of donor PNPLA3 c.444G allele." (PMID 35096933, 2021). "The I148M variant of PNPLA3 has shown an association with the progression of liver fibrosis and steatosis, and in the occurrence of hepatocellular carcinoma." (PMID 33622266, 2021). "The PNPLA3 I148M variant has been associated with steatosis, NAFLD, NASH, and hepatocellular carcinoma." (PMID 34685739, 2021). "We found that the concomitant deficiency of Pnpla3 and Mgl causes complex changes in FA metabolism and aggravates steatosis and inflammation." (PMID 33672787, 2021). "A genetic variant (I148M) in patatin-like phospholipase domain-containing protein 3 (PNPLA3) is associated with steatosis, inflammation, cirrhosis and HCC." (PMID 34646672, 2021). "The PNPLA3 rs738409[G] allele (causing an I148M substitution) associates with both steatosis, NASH, cirrhosis, and hepatocellular carcinoma, and predicts an earlier age at NAFLD diagnosis." (PMID 33804302, 2021).
steatosis (continued). "In this manuscript, we focus on the baseline prevalence and associations of PNPLA3 with a subset of the cohort related to steatosis, hepatic injury, and fibrosis." (PMID 33800964, 2021). "PNPLA3 encodes for a lipase that hydrolyzes triglycerides, and c.444C>G (p.I148M; rs738409) was associated with an increased risk of developing steatosis in multiple disorders, from NAFLD to hepatitis B and C." (PMID 34572285, 2021). "For example, rs738409, a functional loss variant of patatin-like phospholipase domain containing 3 (PNPLA3) (I148M), has been associated with the severity of steatosis and fibrosis as well as the presence of NASH." (PMID 34446002, 2021). "In this regard, PNPLA3 is the first locus to be reproducibly and strongly related to susceptibility to steatosis and fibrosis/cirrhosis in liver diseases." (PMID 33546191, 2021). "Pnpla3 deficiency aggravates the effects of Mgl deletion on steatosis and inflammation in the liver under HFD challenge." (PMID 33672787, 2021). "The mechanism by which the I148M variant induces the development of steatosis seems related to the accumulation of the mutated PNPLA3 protein." (PMID 33578702, 2021). "We also found that a low hepatic expression of PNPLA3 mRNA was independently associated with predominant Ld-MaS vs. nil-Steatosis." (PMID 34198853, 2021). "It has been reported that liver transplant recipients with G allele in position rs738409 of PNPLA3 were at increased risk for graft steatosis." (PMID 34876018, 2021). "By 2019, several genome-wide association studies had firmly established PNPLA3 I148M as a genetic modifier of steatosis in the liver and a risk factor for steatohepatitis, fibrosis, and HCC." (PMID 34847156, 2021). "It has been shown that the presence of linoleic acid and oleic acid is associated with increased expression of PNPLA3 and overexpression of PNPLA3 in those with I148M variant has been shown to lead to steatosis." (PMID 34065978, 2021). "There are relatively limited data regarding the role of PNPLA3 single nucleotide polymorphisms (SNPs) in the development of steatosis, liver injury and fibrosis among those with HIV infection." (PMID 33800964, 2021). "PNPLA3 rs738409 polymorphism is the most studied genetic variant for steatosis after liver transplantation and has been previously reported as a risk factor." (PMID 34876018, 2021). "Such dissociation between insulin resistance and steatosis has been also reported for other gene variants such as PNPLA3." (PMID 32394396, 2020). "The underlying mechanisms whereby the p.I148M variant induces steatosis development seems to be related to the accumulation of the PNPLA3 mutated protein on the lipid droplet surface." (PMID 32340286, 2020). "Single nucleotide polymorphism in the PNPLA3 gene has been associated with steatosis, fibrosis and elevated transaminases in individuals with NAFLD, with variations within different regions of India." (PMID 32943747, 2020). "In this cohort, the variant did not impact on hepatic fat accumulation, but stratifying patients for the PNPLA3 I148M risk variant, the rs236918 variation seems to be also associated with more severe steatosis." (PMID 32340286, 2020). "The human patatin-like phospholipase domain-containing 3 (PNPLA3) SNP was associated with a portal pattern of steatosis, inflammation and fibrosis." (PMID 31726658, 2019). "Lines of evidence showed that IL28B and PNPLA3 polymorphism were associated with advanced liver diseases and steatosis in chronic hepatitis C." (PMID 29470547, 2018). "Results from studies in large cohorts underscored that the PNPLA3 p.I148 variant plays an important role in the progression from steatosis to fibrosis and cirrhosis." (PMID 30161167, 2018). "While the I148M variant determines a loss of enzymatic activity and steatosis development seems to depend upon the accumulation of the mutant 148M PNPLA3 on the surface of lipid droplets, the deletion of the protein has no pathological phenotype." (PMID 30513996, 2018).
steatosis (continued). "The strongest genetic determinant of NAFLD is the PNPLA3 locus, which has been consistently associated with increased liver fat synthesis (steatosis) in genome-wide association studies." (PMID 29375475, 2017). "PNPLA-3 is associated with lipid accumulation in hepatic tissues, especially in steatosis progression." (PMID 28264426, 2017). "We observed that the associations between PNPLA3 rs738409 GG genotype and steatosis was significant (OR: 2.16; 95% CI 1.26-3.72)." (PMID 29258449, 2017). "By reason of its biopsy-proven, steatosis-predisposing characteristics in parallel to that of other SNPs, PNPLA3 rs1010023 is supposed to function in a loss-of-function pattern." (PMID 28695131, 2017). "After adjusting for age, gender, BMI, HOMA-IR, ethnicity/color, alcohol use, HCV genotype 3, and TM6SF2 genotypes, the association between PNPLA3 rs738409 GG genotype and steatosis remained significant in the recessive (p=0.01) model." (PMID 29258449, 2017). "In biopsies with steatosis >0 obtained from PNPLA3 variant carriers, the steatosis distribution pattern was panacinar in 14, azonal in 10, zone 3 in 8, and zone 1 in 4 cases." (PMID 29150621, 2017). "Using a 443 patient training set, protein biomarker discovery was performed using the highly multiplexed SOMAscan® proteomic assay, a set of 19 clinical variables, and the steatosis predisposing PNPLA3 rs738409 single nucleotide polymorphism genotype status." (PMID 28266614, 2017). "This study assessed the contribution of the PNPLA3 rs738409 polymorphism with regard to the steatosis and degree of liver fibrosis in Brazilian patients diagnosed with chronic hepatitis C." (PMID 29258449, 2017). "Some studies have indicated that the rs738409 polymorphism of the PNPLA3 gene is associated with steatosis and the progression of advanced fibrosis." (PMID 29258449, 2017). "In consistent with other steatosis-related SNPs (i.e., rs738409, rs2281135, rs139051, and rs2294918), PNPLA3 rs1010023 seems to be loss-of-function in the aspect of TG hydrolysis." (PMID 28695131, 2017). "Increased PNPLA3 expression is associated with steatosis, with higher levels correlating with greater severity." (PMID 28883965, 2016). "Regarding histopathological features, we only found a direct association between PNPLA3 expression and degree of steatosis in the total MO group (r = 0.441, p = 0.001)." (PMID 27128907, 2016). "Contradictory data about the impact of the rs738409 steatosis-related polymorphism within PNPLA3 gene on liver fibrosis progression in HIV/hepatitis C virus (HIV/HCV)-coinfected patients have been reported." (PMID 27973562, 2016). "Intriguingly, one of these changes concerned the increased expression of Pnpla3 which has frequently been found to be associated with steatosis where it acts as a downstream gene of SREBP-1c to promote lipid accumulation." (PMID 27185526, 2016). "Carriage of the G allele in PNPLA3 was associated with an increased risk of steatosis in Swiss patients infected with HCV genotype non-3." (PMID 26389885, 2015). "It demonstrated that average ALT after interferon therapy ≥ 40 IU/l, IL28B TG/GG, PNPLA3 CG/GG, and steatosis grade ≥ 1 were risk factors associated with rapid fibrosis progression." (PMID 26352693, 2015). "A number of candidate genes including PNPLA3 were investigated, and rs738409 was found to be significantly associated with histological features of increased steatosis and hepatocyte ballooning." (PMID 26462272, 2015). "The GG genotype of PNPLA3 in patients with NAFLD has been associated with more severe steatosis, presence of NASH, and fibrosis." (PMID 26064107, 2015). "Stepwise logistic regression analysis revealed that the strongest factor independently associated with steatosis was the carriage of the PNPLA3 rs738409 GG genotype (odds ratio [OR]/95% confidence intervals [CI]:2.34/1.557–3.515, P < 0.001)." (PMID 26139292, 2015).
steatosis (continued). "A genetic variant in adiponutrin (PNPLA3) gene, rs738409 C/G, is associated with steatosis, severity, and progression of liver fibrosis in CHC patients, and predicts treatment outcome in difficult-to-cure HCV-infected patients with advanced fibrosis." (PMID 26389885, 2015). "Within the patients with NAFLD, degree of steatosis was found to be significantly associated with this variant, independently of PNPLA3 genotype, age, sex and BMI." (PMID 26462272, 2015). "The study found that PNPLA3 was significantly associated with increased histological steatosis only, with an additive effect." (PMID 26462272, 2015). "The study found the PNPLA3 rs738409 variant was associated with moderate-severe steatosis (grade 2–3) by univariate analysis, but the relationship did not persist after Bonferroni correction." (PMID 26462272, 2015). "Another important finding of the present study is that the PNPLA3 G allele was associated with time-dependent progression of fibrosis and steatosis grade." (PMID 26352693, 2015). "By using the dominant model, the factors associated with steatosis included carriage of the PNPLA3 rs738409 CG/GG genotype (OR/CI:1.31/1.013–1.703, P = 0.04), BMI (OR/CI: 1.13/1.084–1.169, P < 0.001) and age (OR/CI:1.02/1.004–1.028, P = 0.006)." (PMID 26139292, 2015). "The association of PNPLA3 148M/M with FPR was more consistent in the presence of grade 2–3 steatosis (p = 0.024), or in the presence of other steatogenic factors: namely infection with genotype 3 (p = 0.005), or overweight (p = 0.05)." (PMID 25171251, 2014). "Effect of PNPLA3 148M/M on (log10) FPR in 247 CHC patients according to steatosis severity and the presence of risk factors for steatosis/altered hepatic lipid metabolism (HCV-G3 and overweight)." (PMID 25171251, 2014). "Recent GWAS and candidate-gene approaches are examples of this wherein a number of SNPs such as the PNPLA3 have been identified that are associated with steatosis, steatohepatitis and more advanced disease." (PMID 23894275, 2013). "Evaluation of the interaction of PNPLA3 with other genetic variants influencing steatosis and NASH, including GCKR, ENPP1 and IRS-1, SOD2, KLF6, LPIN1, and possibly other SNPs will be instrumental to achieve these goals." (PMID 23394097, 2013). "To date, PNPLA3 polymorphisms are the best validated susceptibility modifiers for steatosis and progressive hepatic injury." (PMID 23394097, 2013). "As discussed in the previous paragraphs, the PNPLA3 rs738409 polymorphism is a strong determinant of hepatic fat accumulation and steatohepatitis, but also influences steatosis and fibrosis progression in CHC." (PMID 23394097, 2013). "Since the discovery of the association between the PNPLA3 mutation and steatosis and steatohepatitis, several additional single nucleotide polymorphisms (SNPs) have been identified to be associated with NASH." (PMID 23894275, 2013). "In an independent cohort of 537 Caucasian HCV-infected patients PNPLA3 rs738490 was also associated with steatosis, fibrosis, and fibrosis progression." (PMID 23342360, 2012). "The PNPLA3 I148M variant is associated with the ultrasonography-determined steatosis degree in Chinese population." (PMID 23176674, 2012). "In the setting of HCV infection, PNPLA3 I148M sequence variant has been extensively associated with steatosis, fibrosis progression, cirrhosis and hepatocellular carcinoma." (PMID 22978414, 2012). "Recently, the functional variant I148M of PNPLA3, a gene likely involved in hepatic triglyceride hydrolisis, has been associated with steatosis severity and with the presence of NASH in the same cohort here studied." (PMID 22927922, 2012). "The research group has recently contributed to unravel the role of PNPLA3 in the progression of liver damage in liver diseases associated with steatosis." (PMID 22898488, 2012).